PODXL (podocalyxin like)
Diseases named in the same sentence as PODXL in open-access papers (continued):
Sharing a sentence is not in itself a finding about the gene and the disease.
endometrial cancer (1 paper, 2024). Primary or metastatic malignant neoplasm involving the endometrium (mucous membrane that lines the endometrial cavity). "PODXL showed upregulation in endometrial cancer in our analysis." (PMID 39186767, 2024).
fibrosis (1 paper, 2025). the formation of excess fibrous connective tissue in an organ or tissue in a reparative or reactive process. "Furthermore, compared to the low-grade fibrosis group, a statistically significant increase in PODXL immunoreactivity was observed in the high-grade fibrosis group (p = 0.004)." (PMID 41462970, 2025).
Flavivirus Infections (1 paper, 2020). Infections with viruses of the genus FLAVIVIRUS, family FLAVIVIRIDAE. "Proteins differentially expressed in flavivirus infections other than Zika include SLC3A2, PODXL, ASNS and LPL." (PMID 32873194, 2020).
Insulin resistance (1 paper, 2019). Increased resistance towards insulin, that is, diminished effectiveness of insulin in reducing blood glucose levels. "Solute carrier family 9, member 3 regulator 1 (SLC9A3R1), PODXL, and PDPN are novel biomarkers for the development of insulin resistance." (PMID 30678306, 2019).
intestinal cancer (1 paper, 2015). "Positive expression of PODXL by both antibodies was associated with intestinal cancer type, but a PODXL-negative tumor proved not to be a prognostic marker in intestinal cancer." (PMID 26674770, 2015).
kidney injury (1 paper, 2024). Trauma to the kidney. "For example, Miller and colleagues reported that a model combining urinary particle concentrations, blood lactate levels, urinary extracellular vesicles positive for PODXL, and miR-125a-5p could predict kidney injury." (PMID 39138396, 2024).
kidney tumors (1 paper, 2013). "Recently, increased PODXL expression has been associated with a subset of aggressive cancers including acute myeloid and lymphoid leukemia, myeloid sarcomas, as well as certain breast, liver, pancreatic and kidney tumors." (PMID 23596468, 2013). "PODXL reportedly increases the aggressive phenotype of numerous types of cancer, including acute myeloid and lymphoid leukemia, myeloid sarcomas, as well as certain breast, liver, pancreatic and kidney tumors." (PMID 23596468, 2013).
melanoma (1 paper, 2020). A malignant, usually aggressive tumor composed of atypical, neoplastic melanocytes. "The Cancer Genome Atlas Skin Cutaneous Melanoma analysis showed that the high expression of DEL-1 and PODXL/mRNA in samples from patients with melanoma was indeed associated with poor survival and could be used as a prognostic marker." (PMID 33172202, 2020).
metastasis (1 paper, 2019). The spread or migration of cancer cells from one part of the body (where they first appeared) to another. "In addition, elevated PODXL expression was positively correlated with advanced tumor stage, high-grade stage and lymph node metastasis, which was consistent with the roles of PODXL in other cancers." (PMID 29748877, 2019).
Obesity (1 paper, 2017). Accumulation of substantial excess body fat. "Moreover, the expression of FGFRL1, PNKD, PODXL, PTPRCAP, SMAD3 and WDR45L based on previously reported data correlated inversely with the methylation levels in the subcutaneous adipose tissue suggesting a potential epigenetic regulation associated to obesity." (PMID 28211912, 2017).
omphalocele (1 paper, 2021). Omphalocele is an embryopathy classified in the group of abdominal celosomias and is characterized by a large hernia of the abdominal wall, centered on the umbilical cord, in which the protruding viscera are protected by a sac. "During embryonic development, PODXL in mesothelial cells is required for retracting the embryonic gut from the umbilical cord, and loss of PODXL leads to gut herniation or omphalocele in 30% of mice." (PMID 34201212, 2021).
preeclampsia (1 paper, 2019). Preeclampsia is a hypertensive disorder of pregnancy that is characterized by new-onset hypertension with proteinuria presenting after 20 weeks of gestation, and depending on mild or severe forms may initially present with severe headache, visual disturbances, and hyperreflexia. "Podocalyxin (PODXL) is significantly increased in early-onset preeclampsia and may represent a novel marker of maternal endothelial cell dysfunction." (PMID 30917529, 2019).
rectal tumours (1 paper, 2013). "In this study we found an excellent concordance between PODXL expression in rectal tumours before and after neoadjuvant irradiation, suggesting that PODXL expression is not affected by radiation therapy." (PMID 23819542, 2013).
Renal Wilm’s Tumor (1 paper, 2025). "We were interested to study the effect of Dapagliflozin and Dapagliflozin-Saxagliptin combination groups on podocyte health by quantifying the exosome expression for Nephrin, Renal Wilm’s Tumor (WT-1) and Podocalyxin like protein 1( PODXL) in urine samples." (PMID 39865301, 2025).
sarcoma (1 paper, 2025). A usually aggressive malignant neoplasm of the soft tissue or bone. "Notably, PODXL promotes FP-RMS transendothelial invasion, a key biological property in sarcoma dissemination, and is a cell surface-expressed protein." (PMID 39448867, 2025).
Ta (1 paper, 2017). "Notably, no membranous PODXL expression was seen in Ta tumours." (PMID 28293425, 2017).
testicular cancer (1 paper, 2024). A primary or metastatic malignant neoplasm that affects the testis. "For instance, miR-199a-5p has been documented to suppress PODXL expression in testicular cancer, suggesting a regulatory role of this microRNA on the gene." (PMID 38879474, 2024).
uterine corpus endometrial carcinoma (1 paper, 2020). A endometrial carcinoma (disease) that involves the body of uterus. "But there were adverse results in kidney renal clear cell carcinoma and uterine corpus endometrial carcinoma, which showed a significant correlation between the low expressed PODXL and poor OS." (PMID 32615943, 2020).
tumor (77 papers, 2009 to 2025). "Studies involving both gain- and loss-of-function approaches have demonstrated that PODXL plays a critical role in tumor progression by enhancing cellular migration, invasiveness, stem cell-like properties, and metastasis across diverse cancer types." (PMID 40843679, 2025). "This emphasizes that mucins such as PODXL require contextual modulation to form part of the tumor-associated, prometastatic bulky glycocalyx." (PMID 36735782, 2023). "PODXL has been shown in gain- and loss-of-function studies to play an essential role in tumor progression by promoting migration, invasiveness, stemness, and metastasis in a variety of cancer cells." (PMID 38203331, 2023). "To circumvent this potential pitfall, we developed an antibody, named PODO447, that selectively targets a tumor-associated glycoform of PODXL." (PMID 38188285, 2023). "Because we and others have shown that loss of PODXL core protein expression cripples tumor growth in vivo, the loss of core protein expression likely explains the slow growth rate observed in relapsing tumors post treatment with PODO447-ADC." (PMID 38188285, 2023). "Elevated PODXL expression is also associated with metastasis and poor clinical outcome in multiple tumor types." (PMID 36735782, 2023). "Instead, it argues for a more selective association with the tumor-specific glycosylation of PODXL that is recognized by the PODO447 antibody." (PMID 38188285, 2023). "Overexpression of PODXL within the tumor tissue was associated with poor prognosis, aggressive invasion, chemoresistance and unfavorable therapeutic effects, supporting its role in BM diseases." (PMID 36671569, 2023). "PODXL has been reported to be overexpressed in a variety of malignancies, and strong cell-membrane expression has been associated with both tumor aggressiveness and poor prognoses in a variety of tumors, including CRC." (PMID 34440856, 2021). "Collective evidence suggests that PODXL overexpression is linked to poor prognosis, more aggressive tumour progression, unfavourable treatment outcomes, and possibly chemoresistance." (PMID 34201212, 2021). "Upregulated PODXL has been reported to be associated with tumor progression via increased cell migration and invasion." (PMID 34440856, 2021). "PODXL is well known to be associated with invadopodia formation and to promote the epithelial-mesenchymal transition, tumor migration and invasion." (PMID 32669966, 2020). "Of note, since PODXL is also expressed in tumor-associated vasculature, immunohistochemistry is the preferable assay for analysis of PODXL expression in a clinically relevant context." (PMID 30355278, 2018). "Proposed mechanisms for PODXL-associated tumorigenesis are increased tumor cell migration, invasion and metastatic potential, possibly by inducing epithelial-mesenchymal transition." (PMID 30355278, 2018). "Membranous PODXL expression was significantly associated with higher T-stage and high-grade tumours (p < 0.001 for both)." (PMID 28293425, 2017). "Univariable Cox regression analysis confirmed the significant association between membranous PODXL expression and a reduced 5-year OS in the entire cohort (HR 3.28; 95% CI 1.89–5.69) and in T1 tumours (HR 2.83; 95% CI 1.04–7.72)." (PMID 28293425, 2017). "The results from the present study, based on analyses of tumours from more than 1100 patients, demonstrate, for the first time, strong significant associations between high protein expression of PODXL and EGFR in CRC." (PMID 27160084, 2016). "Podocalyxin-like 1 (PODXL) is a cell-adhesion glycoprotein associated with aggressive tumor phenotype and poor prognosis in several forms of cancer." (PMID 26674770, 2015). "In PB-type tumours, membranous PODXL expression was significantly associated with female sex (p = 0.005), with location to the pancreas (p = 0.005), and with poor differentiation grade (p = 0.044)." (PMID 26028992, 2015).
tumor (continued). "In PB-type tumours, PODXL expression was significantly associated with female sex (p = 0.005), location to the pancreas (p = 0.005), and poor differentiation grade (p = 0.044)." (PMID 26028992, 2015). "Podocalyxin-like 1 (PODXL), an anti-adhesive transmembrane sialomucin, is associated with an aggressive tumour phenotype and poor prognosis." (PMID 25004863, 2014). "Associations of PODXL expression and tumour location with other clinicopathological variables were explored by Fisher’s exact-test, linear-by- linear association test, and binary logistic regression." (PMID 25004863, 2014). "Since then, PODXL has been found to be overexpressed in numerous cancer types and associated with a more aggressive tumour phenotype and poor outcome in breast, prostate, colorectal ovarian and bladder cancer." (PMID 23819542, 2013). "As such, the REMBRANDT data reflects PODXL staining in both tumor cells and also the associated vasculature in the sample." (PMID 24146797, 2013). "Podocalyxin-like 1 (PODXL) is a cell-adhesion glycoprotein and stem cell marker that has been associated with an aggressive tumour phenotype and adverse outcome in several cancer types." (PMID 22769594, 2012). "PODXL has been associated with an aggressive tumour phenotype and adverse outcome in several cancer types." (PMID 22769594, 2012). "Because we and others have shown that loss of the PODXL core polypeptide expression cripples tumor growth these data suggest that a PODO447-ADC targeted strategy could prove highly effective with a lower risk of immune escape." (PMID 38188285, 2023). "Furthermore, PODXL knockdown cells exhibit significantly diminished tumour migration, invasion, as well as proliferation and colony formation, indicating that PODXL expression is associated with tumour aggression through FAK/paxillin/cortactin signalling." (PMID 34201212, 2021). "As PODXL is expressed by platelets in association with tumour cell–selectin interactions, PODXL has been speculated to confer mechanisms in tumour for immune evasion." (PMID 34201212, 2021). "Furthermore, tumours with deficient PODXL also exhibit impaired metastasis and significant reductions in the proportion of cells colonising a secondary site." (PMID 34201212, 2021). "Furthermore, a variable in-frame deletion and a missense variant of PODXL were associated with increased risk of prostate and tumor aggressiveness." (PMID 32046309, 2020). "The influence of TGF-β on PODXL and tumor aggressiveness might provide an explanation of the mechanism indicative of the association between high PODXL and reduced survival among patients." (PMID 32587323, 2020). "Interestingly, PODXL has been implicated in the interaction of tumor cells to E-selectin as well as to L-selectin." (PMID 32046309, 2020). "Moreover, PODXL was overexpressed in poor differentiation and increasing PODXL expression was significantly associated with worse tumor differentiation." (PMID 29748877, 2019). "A later finding is that tumor-cell-specific PODXL expression is associated with a more aggressive phenotype and adverse outcome in several cancer types, for example, in breast, prostate, ovarian, colorectal, urothelial bladder, pancreatic, and periampullary cancer." (PMID 26674770, 2015). "Moreover, being a CD34-related protein, PODXL is expressed on vascular surfaces, and thus, present in various amounts in the tumour-associated stroma." (PMID 22769594, 2012). "In addition, the result that membrane-expressed PODXL was associated with poor survival, further supported the deduction that PODXL promoted tumor progression by enhancing the motility and invasiveness of tumor cells." (PMID 32615943, 2020). "PODXL is a significant clinical indicator for tumor prognosis and detection, the expression level and location in tumor tissues, and even the serum concentration of which could be associated significantly with tumor progression." (PMID 32615943, 2020).
tumor (continued). "Next, we investigated whether PODXL is associated with tumor phenotype in OSCC cell lines." (PMID 29854293, 2018). "Moreover, PODXL has been shown to be overexpressed in a variety of malignancies, and associated with a more aggressive tumour phenotype and poor prognosis in breast, prostate, colorectal, ovarian, renal, pancreatic and bladder cancer, as well as in glioblastoma and astrocytoma." (PMID 27160084, 2016). "Analysis of combined PODXL expression (low-moderate-high categories) with clinicopathological parameters showed significant associations between high PODXL expression and poor differentiation (p < 0.0001), advanced stage (p < 0.0001), and tumour side (p = 0.003)." (PMID 25004935, 2014). "Despite the therapeutic potential of anti-PODXL monoclonal antibodies (mAbs), their further development has been limited by concerns regarding potential on-target off-tumor toxicities." (PMID 40843679, 2025). "A specific editing event in the PODXL gene demonstrates ADAR2’s functional role in tumor suppression." (PMID 40852728, 2025). "Functional studies have demonstrated that reducing PODXL expression not only diminishes colony formation but also significantly impairs the metastatic potential of tumor cells." (PMID 40508013, 2025). "PODXL knockdown reversed the tumor cell aggregation induced by the knockout of β-galactoside α2,6-sialyltransferase 1 (ST6GAL1), which catalyzes the addition of α2,6-sialic acid onto terminal glycans on glycoproteins." (PMID 40843679, 2025). "In contrast, ADAR2 functions as a site-specific tumor suppressor, editing key targets, such as PODXL, to impede invasion and progression." (PMID 40852728, 2025). "PODXL is a transmembrane glycoprotein that plays a crucial role in mediating cell adhesion and it is actively involved in the metastatic dissemination of tumor cells." (PMID 40508013, 2025). "Despite the therapeutic potential of anti-PODXL mAbs, their further development has been limited by concerns regarding potential on-target off-tumor toxicities, particularly to normal kidney podocytes and vascular and lymphatic endothelial cells." (PMID 40843679, 2025). "ScRNA-seq analysis revealed that PODXL was predominantly expressed in tumor endothelial cells (TECs) of CC, which was corroborated by tumor section staining." (PMID 39294825, 2024). "All HGSC tumour tissues examined here (n = 17) were positively immunostained for PODXL although the levels varied." (PMID 38553472, 2024). "We and others previously showed that inactivation of PODXL in cancer cell lines cripples their ability to form tumors in xenografted mice and correlates with a decrease in tumor-initiating cell (TIC) frequency in vivo." (PMID 38188285, 2023). "One of these mAbs, PODO447, exhibits exquisite specificity for a tumor glycoform of PODXL but lacks reactivity with normal adult human tissue." (PMID 38203331, 2023). "Ezrin and NHERF-1/2 are adaptor proteins that have diverse binding partners and facilitate the interaction of PODXL with the cytoskeletons of tumor cells." (PMID 38203331, 2023). "We also showed that antibodies targeting a functional domain of PODXL can block tumor growth in xenografts." (PMID 38188285, 2023). "Given that the function of PODXL in normal tissues is also required, it is essential to identify the tumor-specific contexts regulating PODXL function." (PMID 36735782, 2023). "This is in contrast to blocking antibodies to the PODXL extracellular domain showing a decrease in tumor burden and metastasis." (PMID 36735782, 2023). "In this regard, it is noteworthy that elegant experiments by Román-Fernández and colleagues have shown PODXL to be a decoy receptor for galectin-3 which modifies its ability to alter integrin-dependent tumor cell invasion." (PMID 38188285, 2023). "PODXL is involved in tumor malignant progression through the promotion of invasiveness and metastasis." (PMID 38203331, 2023).